CCL22 (C-C motif chemokine ligand 22)
Diseases named in the same sentence as CCL22 in open-access papers (continued):
Sharing a sentence is not in itself a finding about the gene and the disease.
Obesity (8 papers, 2018 to 2024). Accumulation of substantial excess body fat. "MDC, also known as CCL22, was upregulated in obesity and linked to endothelial dysfunction." (PMID 38455231, 2024). "In this model (adjusted R2 = 0.22) FEP remained a significant predictor of elevated CCL22 (β = 245.3, p = 0.0019), while also smoking (β = 308.0, p = 0.0004), olanzapine use (β = 209.7, p = 0.036) and obesity (β = 303.2, p = 0.0042) were associated with CCL22 levels." (PMID 32179746, 2020). "As a result, the CCL22/CCR4 axis represents a promising therapeutic target for preventing the development of obesity and other metabolic disorders, such as insulin resistance." (PMID 38924414, 2024). "Therapeutically, given the ability of CCL22 to induce beige adipocyte thermogenesis and reduce obesity, its therapeutic potential in metabolic diseases is feasible and should be further explored." (PMID 38924414, 2024). "In mice, increasing CCL22 levels prevents diet-induced obesity (DIO) and increases energy expenditure." (PMID 38924414, 2024). "In the present study, we reveal that MDC CCL22, a protein whose expression increases in response to cold and decreases in obesity, acts as a positive regulator of local LN-mediated beiging of iWAT and thermogenesis." (PMID 38924414, 2024). "Future in vivo studies in an animal model of obesity are required to delineate the potential benefit of altering the CCR4/CCL17/CCL22 signalling in vivo and assess the therapeutic window of CCR4 inhibition." (PMID 37124725, 2023). "We used a general linear model with CCL22 level as the dependent variable to adjust for the effects of smoking, obesity, and olanzapine use, and in addition included a covariate for study site (HEPS or TEPS)." (PMID 32179746, 2020). "Taken together, our findings strongly suggest that the ERK1/2 signaling pathway could be involved in CCL17 and CCL22 effects in obesity-related endothelial dysfunction." (PMID 37124725, 2023). "Serum CCL22 level was associated with obesity, smoking, and olanzapine use, but not with sex, cannabis use, or other antipsychotic use in patients." (PMID 32179746, 2020). "Taking advantage of a previously established obesity and weight loss study, which was alternate day fasting (ADF) combined with a low carbohydrate diet (30% carbohydrates, 35% protein, and 35% fat), we asked if CCL22 played a role in obesity and ADF-mediated weight loss." (PMID 38924414, 2024). "Our results of elevated CCL17 and CCL22 levels in peripheral blood from morbidly obese patients suggest that these chemokines may play a role in leukocyte trafficking and endothelial dysfunction in obesity, in addition to their role as chemoattractants in the adipose tissue milieu." (PMID 37124725, 2023). "Our data collectively show that decreased CCL22 signaling in humans may contribute to the impairment of WAT beiging and the development of obesity." (PMID 38924414, 2024). "Thus, CCL22, through its interaction with its receptor CCR4, establishes the local microenvironment to regulate adipose beiging and energy homeostasis, offering therapeutic potential for preventing obesity and related metabolic disorders." (PMID 38924414, 2024). "Interestingly, levels of plasma regulatory factors (IL1RA, PDGF, CCL22) were significantly elevated, whereas those of IL-27, which activates monocytes via the STAT1 signaling pathway, were lower in plasma of mothers with obesity at T3." (PMID 34195568, 2021). "In addition to elevated levels of adipokines and pro-inflammatory cytokines, we observed increased plasma levels of innate cell chemo-attractants CCL22 and IL-8 as described for non-gravid obesity." (PMID 30131724, 2018).
Sepsis (8 papers, 2010 to 2026). Sepsis is defined as life-threatening organ dysfunction caused by a dysregulated host response to infection. "In our first set of experiments, we demonstrated that CCR4, the receptor for CCL17 and CCL22, contributes to the establishment of an inadequate innate immune response during severe sepsis." (PMID 26197455, 2015). "Other experiments, however, have found a protective role for CCL22/MDC, a CCR4 ligand, in a cecal ligation and puncture (CLP) model of sepsis in mice." (PMID 21206747, 2010). "Decreased CCL1 levels, but not CCL22, distinguished acute pancreatitis from sepsis at all time points." (PMID 42091942, 2026). "This is further reinforced by the fact that the M1 cytokines, IL1, IL‐6 and TNF are consistently increased in the hippocampus late after sepsis, and IL‐10 has some peaks during sepsis evolution and CCL‐22 is not increased at all." (PMID 31654493, 2020). "Minocycline treatment prevented the decrease of CCL‐22 expression at day 3, but in general, there was no regulation of this marker after sepsis." (PMID 31654493, 2020). "Furthermore, colon ascendens stent peritonitis (CASP)-induced sepsis in mice has been shown to increase CCL17 and CCL22 mRNA levels in the spleen and liver." (PMID 26197455, 2015). "Furthermore, CCL22 signaling through CCR4 has been shown to promote the formation of cell–cell contacts and interaction with regulatory T cells, as well as regulatory T cell–mediated suppressive activity during severe sepsis." (PMID 40682363, 2025).
dermatitis (7 papers, 2012 to 2025). An inflammatory process affecting the skin. "The function of CCL22 in radiation-caused dermatitis should be investigated in the future." (PMID 33707490, 2021). "The CCR4 specific ligands, CCL17 and CCL22, induce persistent immune cell accumulation at skin inflammation sites." (PMID 34451592, 2021). "Stimulation with TNF-α/IFN-γ induces the production of pruritic cytokines and chemotactic chemokines in keratinocytes such as TSLP, IL-31, CCL17/TARC, and CCL22/MDC, further expanding skin inflammation with the recruitment of major T cell lineage, Th2 cells, resulting in epidermal damage." (PMID 37958804, 2023). "IL-31 may enhance skin inflammation through the induction of several chemokine genes such as CCL17, CCL22 and CCL1 in human keratinocytes which subsequently leads to the recruitment of T-cells, and in turn may become new sources of IL-31." (PMID 22853438, 2012).
multiple sclerosis (7 papers, 2013 to 2023). A progressive autoimmune disorder affecting the central nervous system resulting in demyelination. "In experimental autoimmune encephalomyelitis (EAE), an animal model of multiple sclerosis caused by immunization of animals with whole myelin or myelin products, CCL22 has a key role in disease progression." (PMID 25970596, 2015). "Increasing evidence from clinical trials indicates the involvement of the CCL17/CCL22/CCR4 axis in the pathogenesis of multiple sclerosis." (PMID 36555280, 2022). "CCL22 levels in CSF have been reported to be elevated in women with multiple sclerosis." (PMID 37893015, 2023). "The CSF milieu in multiple sclerosis has been intensively studied, and we could confirm a significant upregulation of CCL22 and CXCL13 in active MS patients." (PMID 31727097, 2019). "For example, Ccl22, the most highly induced gene in B cells isolated from BT co-cultures, is typically produced by macrophages and dendritic cells and is found at elevated concentrations in the CNS of multiple sclerosis (MS) patients." (PMID 23505568, 2013). "CCL22 has also been associated with non-psychotic neuropsychiatric diseases, including temporal epilepsy, autism, several forms of encephalitis, and multiple sclerosis." (PMID 25970596, 2015). "Cerebrospinal fluid levels of CCL22 and CCL17 are elevated in patients suffering from multiple sclerosis." (PMID 36555280, 2022).
periodontitis (7 papers, 2015 to 2025). An acute or chronic inflammatory process that affects the tissues that surround and support the teeth. "IL‐2, ATRA, IL‐33, and chemokine pathways like CCL22 offer promising strategies for enhancing Treg function and restoring immune balance in periodontitis." (PMID 41399014, 2025). "In periodontitis, chronic periodontitis patients showed high levels of CCL22 and CCR4 compared with healthy donors." (PMID 34177907, 2021). "Specifically, experimental periodontitis in IL-4 knockout mice shows an almost total reduction of Tregs and CCL22 production/expression." (PMID 29805313, 2018). "It was early observed in murine and canine experimental periodontitis that the release of CCL22 particles could recruit more Treg cells to inflammatory sites, and significantly reduce the alveolar bone resorption." (PMID 34177907, 2021). "Furthermore, in experimental periodontitis, CCR4KO mice and the blockade of CCL22 in WT mice both showed impairment of Treg migration, accompanied by the expansive osteoclastogenic cytokine and increased inflammatory bone loss." (PMID 34177907, 2021). "Moreover, the migration of CD4+ CD25+ T cells to periodontitis that affected gingival tissues seemed to be dependent on CCL17 and CCL22 expression by the local inflammatory infiltrate, which recruits Treg expressing CCR4 or CCR8." (PMID 29805313, 2018). "The presence or absence of periodontitis was assessed and the peripheral blood (PB) concentrations of IL-6, immunosuppressive cytokines (VEGF, TGF-β1, and CCL22) and proportion of T regulatory cells (Treg, CD3 + CD4 + CD25 + Foxp3 +) were measured." (PMID 35804048, 2022).
tongue squamous cell carcinoma (7 papers, 2019 to 2024). A squamous cell carcinoma that arises from the tongue. "The C-C motif chemokine ligand 22 (CCL22) and C-C chemokine receptor 7 (CCR7) have been reported to be highly expressed in tongue squamous cell carcinoma (TSCC) and associated with poor prognosis such as lymph node metastasis." (PMID 35480305, 2022). "CCL22, mainly synthesized by M2 macrophages, contributes to a deterioration of clinical outcomes of patients with tongue SCC." (PMID 35860473, 2022). "CCL22 was found in macrophages of tongue squamous cell carcinoma." (PMID 31842422, 2019). "CCL22, an immunosuppressive cytokine, facilitates Tregs infiltration in the HPV-related tongue squamous cell carcinoma." (PMID 31988638, 2020). "CCL22 expression by macrophages is modulated through the IL-4/STAT6 signaling pathway, which is pivotal for T cell differentiation into Th2 cells and crucial for CCL22 and VEGF-C expression in tongue squamous cell carcinoma, contributing to lymph node metastasis." (PMID 39286635, 2024).
atherosclerosis (6 papers, 2016 to 2025). A disease characterized by the build-up of fatty material and calcium deposition in the arterial wall resulting in partial or complete occlusion of the arterial lumen. "The protective effect of RPL13 on atherosclerosis may be related to its translational silencing activity: the deletion of RPL13 promotes the translation of mRNAs for CCL22, CXCL13, and CCR3 in macrophages, causing increased expression of inflammatory cytokines." (PMID 36617563, 2023). "In summary, RPL13 inhibits macrophage-induced inflammation and atherosclerosis by inhibiting the translation of inflammatory genes such as CCL22, CXCL13a, and CCR3." (PMID 36617563, 2023). "Apoe knockout mice with a high cholesterol diet were found to have significantly higher CCL22 serum levels than similar mice on a regular diet, contributing to the progression of atherosclerosis." (PMID 31393916, 2019). "To validate this mechanism in our model, we first examined whether CCL22 levels were elevated in atherosclerosis." (PMID 41266856, 2025). "Cluster 5 showed a gene expression profile that was characterized by the expression of Btla, Ccr7, Tbc1d4, Ccl22, and Ly6d revealing a population of MoDC/DC cells present in the aortas that were independent of the atherosclerosis predisposition or the diet." (PMID 35159221, 2022). "Unlike acute myocardial infarction, where CCL17/CCL22 competition occurs transiently during acute inflammation, our study reveals that this chemokine interplay also exists in atherosclerosis, suggesting a chronic and persistent regulatory mechanism in immune cell recruitment and plaque progression." (PMID 41266856, 2025).
Autoimmunity (6 papers, 2017 to 2021). The occurrence of an immune reaction against the organism's own cells or tissues. "In vivo CCL22 deficiency studies are urgently needed to elucidate CCL22 biology in relation to infection, autoimmunity, and cancer." (PMID 29099057, 2017). "Via the control of T cell migration and cytokine production, CCL22-producing CD11bhigh macrophages play a key role in the development of autoimmune lesions in the salivary glands." (PMID 30467506, 2018). "Analysis of CD11b-conditional CCL22 gene knockout mouse in the next study will help define the in vivo function of CCL22 in autoimmunity." (PMID 30467506, 2018). "Our data suggest that the CCL22/17–CCR4+ Treg axis may be involved in long‐term disease tolerance in patients with autoimmunity‐mediated renal disease." (PMID 33163184, 2020). "Interestingly, the immunomodulatory properties of CCL22 in autoimmunity involve Treg cell responses." (PMID 29099057, 2017). "The aim of this review is to highlight the involvement of a C-C class chemokine/receptor axis, consisting of C-C chemokine ligands 17 (CCL17) and 22 (CCL22), and C-C chemokine receptor 4 (CCR4), in CNS autoimmunity." (PMID 29099057, 2017).
colorectal cancer (6 papers, 2019 to 2023). A primary or metastatic malignant neoplasm that affects the colon or rectum. "However, studies conducted on CCL22 expression and Th2 cells in cancers are limited and indicate that CCL22 expression is a risk prognostic factor in breast and colorectal cancer." (PMID 34391381, 2021). "What is more, one study showed that the loss of miR-34a can increase CCL22 expression and promote the development of colorectal cancer after an infection by the bacterium Citrobacter, while the NF-KB signaling pathway also plays an important role in the development of colorectal cancer." (PMID 35295948, 2022). "High amounts of CCL22 expressed in M2 macrophages enables colorectal cancer to be resistant to chemotherapy." (PMID 35805111, 2022). "M2 macrophages decreased the inhibitory effect of 5-fluorouracil (5-FU) on colorectal cancer cells migration and invasion by secreting CCL22, and declined the apoptosis induced by 5-FU." (PMID 35805111, 2022). "Gut microbiota infection can induce the expression of some chemokines, including CCL22, in colorectal cancer." (PMID 35295948, 2022). "High expression of CCL22 in M2 macrophages confers resistance to 5-fluorouracil in colorectal cancer." (PMID 31842422, 2019). "Our analysis showed that F. nucleatum infection could increase CCL22 expression and influence the NF-KB signaling pathway in two kinds of colorectal cancer cells." (PMID 35295948, 2022). "Additionally, the secretion of CCL22 by M2-like macrophages in colorectal cancer was proven." (PMID 31842422, 2019). "For example, CCL22 promotes 5-FU-mediated CRC chemoresistance and EMT through PI3K/AKT signaling, and contributes to poor prognosis in colorectal cancer." (PMID 36334221, 2023).
esophageal squamous cell carcinoma (6 papers, 2018 to 2025). Esophageal squamous cell carcinoma (ESCC) is a type of esophageal carcinoma (EC) that can affect any part of the esophagus, but is usually located in the upper or middle third. "A recent study showed that CCL22 was abundantly expressed by tumor-associated macrophages (TAMs) from humans in esophageal squamous cell carcinoma (ESCC) tissues." (PMID 37198402, 2023). "In esophageal squamous cell carcinoma (ESCC), stromal TAM-derived CCL22 activates the DGKα/NF-κB pathway, upregulating multiple ATP-binding cassette transporters and reducing intracellular cisplatin accumulation, thereby promoting cisplatin resistance." (PMID 41417432, 2025).
Hodgkins lymphoma (6 papers, 2021 to 2023). A heterogeneous group of malignant lymphoid neoplasms of B-cell origin characterized histologically by the presence of Hodgkin and Reed-Sternberg (HRS) cells in the vast majority of cases. "Meanwhile, high levels of CCL17 and CCL22 were detected in a variety of tumors, such as lung cancer, gastric cancer, B-cell non-Hodgkin’s lymphoma, Hodgkin’s lymphoma, and peripheral T-cell lymphoma." (PMID 38077392, 2023). "In lymphomas, CCL17 was specifically expressed in classical Hodgkin’s lymphoma, whereas CCL22 was expressed in nodular lymphocyte-predominant Hodgkin’s lymphoma and B-cell non-Hodgkin’s lymphoma." (PMID 38077392, 2023). "High levels of CCL22 have been found in various types of human tumors such as breast, lung, gastrointestinal, and nasopharyngeal tumors, B–CLL, and Hodgkin lymphoma." (PMID 37259456, 2023). "Previous study also showed that the chemotherapy-sensitive Hodgkin lymphoma patients had frequent gains of 16q13, a chromosomal region known to house genes that regulate T-cells trafficking or NF-ĸB activation (CX3CL1, CCL22, CCL17, DOK4, and IL10)." (PMID 37153002, 2023). "This analysis highlighted that many KEGG Hodgkin lymphoma pathway genes are jointly induced by TES1 and TES2 signaling in LCLs, including CCL22, BCL3, cRel, IRF4, STAT3, STAT6, and CD70, each of which has prominent roles in Hodgkin lymphoma pathogenesis." (PMID 38009935, 2023). "Patient samples from lymphoblastic (Hodgkin lymphoma) and epithelial (nasopharyngeal carcinoma; NPC) EBV+ tumors revealed CCL17 and CCL22 expression of both tumor cell-intrinsic and -extrinsic origin, depending on tumor type." (PMID 35025968, 2022).
pancreatic cancer (6 papers, 2019 to 2025). "In a separate study, both mouse and human pancreatic cancers were demonstrated to over-express the chemokine, CCL22." (PMID 31544847, 2019). "In our study, the candidates stood out as being exceptionally strongly regulated in the cocultures over the pancreatic cancer and RAW264.7 monocultures, namely the previously discussed CCL2 and CCL22 for Panc02 cells and CCL5 for PDA6606 cells." (PMID 40282185, 2025). "In a Pan02 pancreatic cancer mouse model, characterized by the secretion of the chemokines CCL17 and CCL22, the use of a CCR4 antagonist (CCR4-351) has shown significant effects in disrupting the CCR4-CCL17/CCL22 chemotactic axis, which effectively blocks the recruitment of Tregs to the TME." (PMID 38500876, 2024).